RPS27 (ribosomal protein S27)
Description:
Component of the small ribosomal subunit. The ribosome is a large ribonucleoprotein complex responsible for the synthesis of proteins in the cell. Required for proper rRNA processing and maturation of 18S rRNAs. Part of the small subunit (SSU) processome, first precursor of the small eukaryotic ribosomal subunit. During the assembly of the SSU processome in the nucleolus, many ribosome biogenesis factors, an RNA chaperone and ribosomal proteins associate with the nascent pre-rRNA and work in concert to generate RNA folding, modifications, rearrangements and cleavage as well as targeted degradation of pre-ribosomal RNA by the RNA exosome.
Synonyms: MPS-1; MPS1; S27; eS27; DBA17
Tractability: Small molecule: an approved drug acts on it; a structure with a bound ligand is known; a high-quality ligand is known; it belongs to a druggable protein family. PROTAC: ubiquitination databases record sites on it; its protein half-life has been measured; a small molecule that binds it is known. Other modalities: a drug acting on it is in phase 2 or 3 trials.
Target class: Other cytosolic protein
Gene: Protein-coding gene on chromosome 1 (153,990,749 to 153,992,333, forward strand). Ensembl gene ENSG00000177954.
Subcellular location: Cytoplasm; Nucleus, nucleolus
Subcellular location (Human Protein Atlas): Cytosol; Endoplasmic reticulum; Nucleoli
Pathways (Reactome):
Metabolism of proteins: Eukaryotic Translation Termination; Formation of a pool of free 40S subunits; Formation of the ternary complex, and subsequently, the 43S complex; GTP hydrolysis and joining of the 60S ribosomal subunit; L13a-mediated translational silencing of Ceruloplasmin expression; PELO:HBS1L and ABCE1 dissociate a ribosome on a non-stop mRNA; Peptide chain elongation; Ribosomal scanning and start codon recognition; SRP-dependent cotranslational protein targeting to membrane; Translation initiation complex formation; ZNF598 and the Ribosome-associated Quality Trigger (RQT) complex dissociate a ribosome stalled on a no-go mRNA
Cell Cycle: Amplification of signal from unattached kinetochores via a MAD2 inhibitory signal; EML4 and NUDC in mitotic spindle formation; Mitotic Prometaphase; Resolution of Sister Chromatid Cohesion; Separation of Sister Chromatids
Disease: SARS-CoV-1 modulates host translation machinery; SARS-CoV-2 modulates host translation machinery; Viral mRNA Translation
Metabolism of RNA: Major pathway of rRNA processing in the nucleolus and cytosol; Nonsense Mediated Decay (NMD) enhanced by the Exon Junction Complex (EJC); Nonsense Mediated Decay (NMD) independent of the Exon Junction Complex (EJC)
Cellular responses to stimuli: Response of EIF2AK4 (GCN2) to amino acid deficiency
Developmental Biology: Regulation of expression of SLITs and ROBOs
Metabolism: Selenocysteine synthesis
Signal Transduction: RHO GTPases Activate Formins
Gene Ontology:
Molecular function: protein binding; RNA binding; structural constituent of ribosome; DNA binding; zinc ion binding
Biological process: ribosomal small subunit biogenesis; rRNA processing; cytoplasmic translation; translation
Cellular component: cytoplasm; cytosolic ribosome; cytosolic small ribosomal subunit; nucleus; postsynaptic density; small-subunit processome; cytosol; nucleoplasm; ribosome; nucleolus
Genetic constraint (gnomAD): Loss-of-function variants: 1 observed, 9.13 expected, observed/expected ratio (o/e) 0.11, 90% interval 0.038 to 0.52. That is too few expected variants to judge how well the gene tolerates losing a copy. Missense variants: 41 observed, 82.46 expected, observed/expected ratio (o/e) 0.5, 90% interval 0.39 to 0.64. Synonymous variants: 37 observed, 27 expected, observed/expected ratio (o/e) 1.37, 90% interval 1.05 to 1.78.
Homologues: Orthologues: tropical clawed frog rps27 (100% identical). Paralogues in human: RPS27L (96% identical).